ZFY (zinc finger protein Y-linked)
Description:
Probable transcriptional activator. Binds to the consensus sequence 5'-AGGCCY-3'.
Synonyms: ZNF911
Tractability: PROTAC: ubiquitination databases record sites on it.
Gene: Protein-coding gene on chromosome Y (2,935,281 to 2,982,512, forward strand). Ensembl gene ENSG00000067646.
Subcellular location: Nucleus
Subcellular location (Human Protein Atlas): Nucleoplasm; Nucleoli
Gene Ontology:
Molecular function: protein binding; DNA-binding transcription activator activity, RNA polymerase II-specific; DNA-binding transcription factor activity, RNA polymerase II-specific; RNA polymerase II cis-regulatory region sequence-specific DNA binding; sequence-specific DNA binding; DNA binding; metal ion binding
Biological process: positive regulation of transcription by RNA polymerase II; regulation of transcription by RNA polymerase II; regulation of DNA-templated transcription
Cellular component: chromatin; nucleus
Homologues: Orthologues: chimpanzee ZFY (99% identical), macaque ZFY (98% identical), pig ZFY (93% identical). Paralogues in human: ZFX (93% identical), ZNF711 (59% identical), ZFAT (22% identical), PRDM15 (19% identical), ZBTB11 (18% identical), ZSCAN2 (16% identical), ZNF792 (16% identical), ZNF304 (15% identical), ZNF256 (15% identical), ZNF551 (15% identical), ZNF583 (15% identical), ZNF587B (15% identical), and 26 more.
Diseases named in the same sentence as ZFY in open-access papers:
ZFY is named in the same sentence as 15 diseases in open-access papers, as found by Europe PMC text mining. Sharing a sentence is not in itself a finding about the gene and the disease. The quoted sentences say what the papers report.
adenoma (1 paper, 2020). A neoplasm arising from the epithelium. "Several of these genes, e.g., EIF1AY, USP9Y, ZFY, TMSB4Y, have been used as gender-specific tissue biomarkers for both normal and tumoural tissues; corticotrope adenomas can now be added to the list of tissues presenting these markers of sexual dimorphism." (PMID 32183012, 2020).
autism (1 paper, 2025). Persistent deficits in social interaction and communication and interaction as well as a markedly restricted repertoire of activity and interest as well as repetitive patterns of behavior. "Future studies will determine how ZFX’s transcriptional regulation of autism risk genes contributes to the FPE in autism, based on comparing ZFX and ZFY in diverse in vitro and in vivo contexts." (PMID 40964017, 2025).
Azoospermia (1 paper, 2021). Absence of any measurable level of sperm,whereby spermatozoa cannot be observed even after centrifugation of the semen pellet. "While the authors proposed that azoospermia was caused by the production of unbalanced gametes due to the formation of quadrivalent configurations in meiosis, an alternative explanation is the failure to silence the ZFY gene in BTAYp which was translocated to the distal half of BTA9." (PMID 34946841, 2021). "This allows us to theorize that, if ZFY is the true meiotic executioner gene and if the derivative 13q;Y synapsed in meiosis with normal 13q, ZFY may have escaped MSCI leading to meiotic arrest and azoospermia." (PMID 34946841, 2021).
glaucoma (1 paper, 2023). Increased pressure in the eyeball due to obstruction of the outflow of aqueous humor. "Database analysis revealed that seven host genes (NEAT1, SAMD12, KDM5D, ZFY, EIF1AY, TXLNGY, and DDX3Y) of nine DEcircRNAs were also differentially expressed in blood samples of patients with glaucoma, and the trend of differential expression of circRNAs and host genes was consistent." (PMID 37805546, 2023).
infertile (1 paper, 2017). "Although mutations in ZFY have not been reported in infertile patients, our findings suggest that ZFY has a key role in spermatogenesis in humans." (PMID 28114340, 2017).
trisomy 18 (1 paper, 2010). Trisomy 18 is a chromosomal abnormality associated with the presence of an extra chromosome 18 and characterized by growth delay, dolichocephaly, a characteristic facies, limb anomalies and visceral malformations. "The ratios of methylated VAPA-APCDD1(chr18) to ZFY(chrY) were higher in maternal plasma samples of 9 male trisomy 18 fetuses than those of 27 male euploid fetuses (Mann-Whitney test, P = 0.029)." (PMID 21152411, 2010).
tumor (7 papers, 2016 to 2024). "In a subsample of patients whose tumours were profiled for RNA (n = 96), feature S(1,−1)SumAverg was significantly associated with the expression of gene MOV10L1, LRP1B, ZFY, PITX2, TRAPPC12, MMGT1 and PPP2R2C (all P < 0.05)." (PMID 36050449, 2022). "As in tumors, the genes ZFY, RPS4Y1, DDX3Y were selected in all of the tissue types for the male vs. tumor analyses in normal samples, and RPS4Y1 was selected in the majority of tissue types." (PMID 26755347, 2016).
cancer (4 papers, 2016 to 2022). A tumor composed of atypical neoplastic, often pleomorphic cells that invade other tissues. "There was a very high-degree of commonality across all the models, with three Y-chromosome genes selected across all 17 cancers (ZFY, EIF1AY, and DDX3Y), RPS4Y1 (also on the Y-chromosome) selected across 15 of 17 cancers, and XIST (on the X-chromosome) selected across 14 of 17 cancers." (PMID 26755347, 2016). "The other 2 members of the ZFX family, ZFY and ZNF711, have not been as well-studied, especially in the cancer field." (PMID 32406922, 2020).
ZFY also shares sentences with these, for which no sentence is quoted: benign prostatic hyperplasia (2 papers); male infertility (1); neurodegenerative disease (1); prostate hyperplasia (1); prostate tumor (1); spermatogenic failure (1); Turner syndrome (1).